DKK1 (dickkopf Wnt signaling pathway inhibitor 1)
Diseases named in the same sentence as DKK1 in open-access papers (continued):
Sharing a sentence is not in itself a finding about the gene and the disease.
tumor (continued). "Similarly, our analyses reveal that DKK1 exhibits a higher level in NB tumor tissues than normal neuronal tissues, as well as a higher gene expression in Neuro-2a and SH-SY5Y cells than HK2 cells." (PMID 40804038, 2025). "Interestingly, Dkk1 is also highly expressed in bone and its deletion exerts profound anti-tumor effects." (PMID 39885132, 2025). "Systemic and bone-specific DKK1 targeting reduce tumor growth." (PMID 39885132, 2025). "DKK1 has been identified as both a tumor suppressor and metastasis promoter." (PMID 40394415, 2025). "Because Dkk1 deletion leads to embryonic lethality, moms and pups were fed a doxycycline-containing diet until weaning to suppress the transgene activation, and mice were orthotopically injected with the PyMT tumor cells when they reached 6–8 weeks of age." (PMID 39885132, 2025). "This suggests that DKK1’s pro-tumor effects are dependent on the lung microenvironment." (PMID 40025612, 2025). "Finally, we demonstrated that TP-0903 significantly diminished the tumor growth and DKK1 expression in xenograft mice." (PMID 40804038, 2025). "In tumorigenesis, DKK1 functions as a tumor suppressor through its inhibition of Wnt signaling." (PMID 40804038, 2025). "This implies that DKK1 may promote tumor growth by modulating the tumor microenvironment, making it a promising target to counteract chemoresistance." (PMID 40862711, 2025). "To assess whether DKK1 levels were also increased in TNBC, we used BALB/c mice orthotopically injected with the 4T1 tumor line and found increased DKK1 in circulation." (PMID 39885132, 2025). "Notably, therapeutic inhibition of the pathway—for example, by targeting Dickkopf-1 (DKK1) with DKN-01—can reshape the tumor immune microenvironment by restoring HLA/MHC expression." (PMID 41050070, 2025). "Previous studies have reported that DKK1 affects immune cells within the tumor." (PMID 40025612, 2025). "Further investigation into the role of DKK1 revealed that its overexpression led to pronounced growth suppression, while siRNA-mediated knockdown of DKK1 slightly increased cell proliferation, confirming DKK1's role as a tumor suppressor and a key effector of genistein's action." (PMID 40969596, 2025). "In vivo studies indicated that these anti-DKK1 antibody leads targeting DKK1 CDR1 are potent in inhibition of tumor growth and may have promising efficacy as cancer immunotherapy due to activation of the Wnt non-canonical pathway." (PMID 40394415, 2025). "Here, we showed that lung fibroblast activated by DKK1 actively produced IL-6 and CCL2, which are representative cytokines identified as the iCAF markers, which raise a notion that iCAFs are activated and promote tumor progression in high DKK1-expressing tumors." (PMID 40025612, 2025). "Additionally, DKK1 has been demonstrated to regulate the accumulation and function of myeloid-derived suppressor cells in the tumor microenvironment, contributing to immunosuppression in cancer." (PMID 39505867, 2024). "This cycle is reinforced by the secretion of tumor factors (dickkopf-related protein 1: DKK-1, sclerostin 1: SOST-1, BMP inhibitor noggin, and activin A) inhibiting osteoblast activity, which is manifested by damaged bone with decreased bone mineral density (BMD)." (PMID 39596154, 2024). "DKK1 can promote the PI3K–AKT signaling pathway in tumor cells and then could induce neuritogenesis and facilitate PNI." (PMID 38525111, 2024). "In summary, DKK1 can promote the PI3K–AKT signaling pathway in tumor cells and then could induce neuritogenesis and facilitate PNI." (PMID 38525111, 2024). "Furthermore, we monitored the HOTTIP/hnRNPA2B1/DKK1 regulatory axis in tumor specimens derived from nude mice." (PMID 38481876, 2024). "DKK1 displayed heightened expression in tumor cells compared to normal epithelial cells." (PMID 39505867, 2024). "Immunohistochemical staining revealed DKK1 expression in the tumor stroma from early tumor growth." (PMID 38334454, 2024).
tumor (continued). "DKK1 is expressed in the tumor microenvironment and in bone." (PMID 38659818, 2024). "Indeed, immune fluorescence images show reduced interactions between NK and tumor cells in the presence of DKK1." (PMID 38659818, 2024). "Previous findings suggested that an excess of glucocorticoids interrupted the Wnt pathway through activation of Wnt-inhibitors, including Dickkopf-1 (Dkk-1), which was reported to be a tumor suppressor in BC as its inhibition leads to increased BC cell migration and invasion." (PMID 38864530, 2024). "To determine if DKK1 modulates the immune landscape of the tumor microenvironment, we profiled the tumor-infiltrating immune populations from IgG or mDKN01-treated mice via flow cytometry, 16 days post tumor inoculation." (PMID 38659818, 2024). "Based on these findings, we considered whether DKK1 may be impacting the ability of NK cells to interact with the tumor cells." (PMID 38659818, 2024). "It was observed that the expression of DKK1 were higher in PDAC tumors than in para-tumor tissues." (PMID 39107271, 2024). "Notably, DKK1 manifested increased expression in tumor cells relative to immune cells and normal epithelial cells." (PMID 39505867, 2024). "91% of all DKK1+ cells were tumor cells and the majority of the remainder were myeloid cells." (PMID 39417106, 2024). "Additionally, MIF released from DKK1+ tumor cells activated CD74, CXCR4, and CD44 on immune clusters." (PMID 39505867, 2024). "Immunostaining of tumors at different stages of development revealed DKK1 expression in the tumor stroma starting from the early stages of tumor development, and it may be involved in early responses of fibroblasts to tumors." (PMID 38334454, 2024). "Similarly, the orthotopic transplantation of PDAC cells to simulate in situ tumor generation showed decreased weight and surface blood sinus formation in OTTs upon DKK1-SE deletion, consistent with STT observations." (PMID 39107271, 2024). "Next, we assessed the link between DKK1 expression and tumor immune cell infiltration." (PMID 38376441, 2024). "DKK1 could promote the PI3K–AKT signaling pathway in tumor cells, and then could induce neuritogenesis and facilitate PNI." (PMID 38525111, 2024). "Systemic or bone-specific DKK1 targeting reduces primary tumor growth." (PMID 38659818, 2024). "Furthermore, our study unveiled that DKK1+ tumor cells amassed within the tumor region in immune exclusion samples, particularly proximal to the tumor boundary." (PMID 39505867, 2024). "A larger percentage Dkk1 reduction was observed in TNBC tumours and cases with advanced G stage." (PMID 38254908, 2024). "Because Dkk1 deletion leads to embryonic lethality, we fed moms and pups with a doxycycline-containing diet until weaning to suppress the transgene activation, and orthotopically injected the PyMT tumor cells when mice reached 6–8 weeks of age." (PMID 38659818, 2024). "We hypothesized that DKK1+ tumor cells inhibited the infiltration of immune components into the tumor area." (PMID 39505867, 2024). "Overall, our findings imply that DKK-1 may indirectly stimulate tumor development by inducing immunosuppressive effects in malignant tumors." (PMID 38376441, 2024). "Local production of DKK1 at tumor site affects tumor immune infiltration." (PMID 38659818, 2024). "Intriguingly, deletion of either source of DKK1 results in a significant anti-tumor effect." (PMID 38659818, 2024). "Additionally, a negative correlation was found between the methylation status of the DKK1 promoter and DKK1 gene expression in these tumor cells." (PMID 39107271, 2024). "To better understand how DKK1 promotes tumor progression in vivo, we performed bulk RNA sequencing of GFP-H2B-mApple-Thy1.1+ PyMT-BO1 cells isolated from orthotopic tumors in WT mice receiving IgG or mDKN01, after exclusion of Ter119+ erythrocytes and CD45+ immune cells." (PMID 38659818, 2024). "Targeting DKK1 as single therapy with a monoclonal antibody has significant anti-tumor effects." (PMID 38659818, 2024).
tumor (continued). "Excessive levels of DKK1 have been shown to facilitate tumor cell proliferation, but it is noteworthy that anti-DKK1 therapy may not only enhance Wnt signaling in osteoblasts but also in tumor cells." (PMID 38886806, 2024). "Dkk1 levels were found to be lower in treated BC tumours than in untreated tumours." (PMID 38254908, 2024). "Additionally, we observed the accumulation of DKK1+ tumor cells within the tumor area in immune-exclusion samples, particularly at the tumor boundary, which inhibited the infiltration of CCL19+ fibroblasts and plasma cells into the tumor area." (PMID 39505867, 2024). "In addition, we previously reported that DKK1 promoted angiogenesis and tumor progression by regulating the VEGFR2-mediated pathway." (PMID 38012711, 2023). "High expression of DKK1 was observed specifically in tumours in the Nicd/Akt/DKK1 group." (PMID 35924447, 2023). "Due to the association of DKK1 with both immune modulation in our in vivo model and worse outcomes in patients with iCCA,18, 24, 25, 26 we sought to explore whether DKK1 expression promotes immune cell recruitment to the iCCA tumour microenvironment." (PMID 35924447, 2023). "Our result showed that DKK1 plays a vital role in the tumor-suppressive function of eMSCs." (PMID 37287079, 2023). "By disabling these anti‐tumour cells, DKK1 promotes tumour growth." (PMID 35924447, 2023). "Targeting DKK1 with a neutralizing antibody is effective at reducing tumour growth in vivo." (PMID 35924447, 2023). "Additionally, the promoting effect of DKK1 on malignant tumor phenotypes needs to be further verified in vivo as well as the effectiveness of anti‐DKK1 therapy against AFPGC." (PMID 37017469, 2023). "The increase in DKK-1 expression in PCa may have direct effects on the cell cycle, thus increasing tumor proliferation." (PMID 37366915, 2023). "Having established a DKK1‐driven increase in TAM2‐like macrophages in our hydrodynamic models, we next sought to explore whether DKK1 expression can promote tolerogenicity in the iCCA tumour microenvironment." (PMID 35924447, 2023). "This suggests that the inhibition of DKK1 could be an effective strategy at reducing tumour growth in a more physiologically and clinically relevant model with an active inflammatory driver, and without the artificial overexpression of DKK1." (PMID 35924447, 2023). "As such, DKK1 targeted and immune modulatory therapies may be an effective strategy in iCCA patients with high DKK1 tumour expression or tolerogenic immune phenotypes." (PMID 35924447, 2023). "It was reported that DKK1, secreted by MSCs, an inhibitor of the Wnt pathway, could inhibit tumor progression in various cancers." (PMID 37287079, 2023). "Finally, we demonstrate that inhibition of DKK1 with the monoclonal antibody mDKN‐01 is effective at reducing tumour burden in two distinct mouse models of the disease." (PMID 35924447, 2023). "Second, we found that DKK1 inhibition increased the anti-tumor efficacy of SOR in HCC." (PMID 38012711, 2023). "Further understanding of the mechanisms governing DKK1's immune modulatory and tumour‐promoting activity in iCCA is required to provide a rationale for patient stratification or therapy combinations in which DKK1 inhibition can be levied in the most effective way." (PMID 35924447, 2023). "In addition, we observed a similar increase in F4/80‐positive cells in KrasG12D/gTrp53 tumours overexpressing DKK1." (PMID 35924447, 2023). "However, there still are several limitations, such as the development of brain penetrant inhibitors of UBA2, RALY, FOXD1, and DKK1 that can be selective against tumor cells as well as more studies for clinical research." (PMID 37906341, 2023). "Having established a role for DKK1 in promoting tumour immune modulation and defined the relationship between DKK1 levels and FOXP3+ cells in a cohort of human samples, we next wanted to test whether DKK1 inhibition was effective at reducing iCCA growth." (PMID 35924447, 2023).
tumor (continued). "In two mouse models of iCCA, the inhibition of DKK1 with DKN-01 resulted in a reduced tumor burden." (PMID 37190050, 2023). "In this study, we investigated whether the inhibition of DKK1 enhances the anti-tumor efficacy of sorafenib in HCC." (PMID 38012711, 2023). "DKK1 has been found to be hypermethylated in several types of tumors, and its tumor suppressor activity can be reversed using demethylation agents, suggesting that hypermethylation of this gene may be a new therapeutic target in metastatic-competent CTCs." (PMID 37717096, 2023). "A recent study has confirmed that DKK1 overexpression promotes VM in NSCLC tumor cells." (PMID 37906341, 2023). "Targeting DKK1 represents a therapeutic opportunity for patients with DKK1 expressing tumours." (PMID 35924447, 2023). "However, the clinical implications for β-catenin according to tumor infiltrative immune cells and DKK1, as an antagonist of Wnt/β-catenin signaling, remains controversial." (PMID 35121803, 2022). "Furthermore, recent studies have shown that elevated DKK1 expression contributes to tumor growth and poor prognosis in a range of cancers, suggesting a role in tumor aggressiveness independent of WNT signaling." (PMID 35712490, 2022). "The role of DKK1 in tumours is controversial and may play different roles in different organs and tumours." (PMID 35907982, 2022). "DKK-1 serum levels correlated strongly with radiological total tumor diameter and with BCLC stages." (PMID 36230730, 2022). "DKK1-promotes differentiation is indispensable for disseminated tumor cell metastatic outgrowth." (PMID 35296660, 2022). "Our previous study found that constitutively high expression of human Dkk-1 in the OS cell line MOSJ-Dkk-1 increases tumour growth rate and bone destruction in mouse models when compared to control lines which manifested tumours primarily as non-osteolytic chondroblastic OS nodules." (PMID 35277659, 2022). "In addition, this study suggests that DKK1 exhibits tumor suppressor activity by blocking the tumor invasion activity of CS-E and by inhibiting β-catenin-dependent Wnt signaling." (PMID 35712490, 2022). "DKK1 protects tumor cells from ferroptosis and is indispensable for metastatic outgrowth." (PMID 36581640, 2022). "Results showed that the selected AGs in our risk model (BAK1, DKK1, and MIF) were negatively related to the infiltration levels of tumor-infiltrating lymphocytes (including T cells, B cells, and macrophages), suggesting a low immunosuppressive activity for HNSCC patients of the high-risk groups." (PMID 35619896, 2022). "It has been strongly suggested that DKK1 may have a proapoptotic effect on tumor cells via the downregulation of β-catenin." (PMID 35355709, 2022). "Moreover, the elevated cAMP induces an increased expression of the secretory protein DKK1, which was reported to promote tumor growth and metastasis in several tumor models." (PMID 35517499, 2022). "Furthermore, we determined that DKK-1 enhances angiogenesis in vitro, and anti-DKK-1 neutralizing antibody inhibits tumor growth in vivo." (PMID 35269944, 2022). "Herein, we demonstrate that through inhibiting Dkk-1 transcription by means of a vivo morpholino (DkkMo), it is possible to (i) reduce the expansion of MOSJ-Dkk-1 tumours in vitro and vivo, (ii) preserve bone volume and architecture in vivo and (iii) stimulate necrosis of the tumour." (PMID 35277659, 2022). "In human PCa models (PC3), DKK1 blockades slowed tumor growth in an NK-cell-dependent manner." (PMID 35892678, 2022). "In a series of studies, it was found that the expression of DKK1 decreased in tumor cells." (PMID 35967426, 2022). "Astrocytes secrete Dkk-1 promoting tumor cell extravasation." (PMID 36439519, 2022). "Importantly, within HPV-positive clinical specimens, DKK1 accumulation was strongly associated with higher histological grade and TNM stage, supporting its potential role as a biomarker for tumor aggressiveness." (PMID 34974279, 2022).
tumor (continued). "Therefore, we further investigated if the clinical outcomes (OS and RFS) differ according to the primary tumor site in patients with positive DKK1 and ß-catenin expression." (PMID 35121803, 2022). "Dickkopf-1 (DKK1) can inhibit the Wnt/β-catenin pathway and promote tumor development." (PMID 36581640, 2022). "For TN-C, it is known that its presence in the mesenchyme results in increased levels of the pro-angiogenic factor VEGF in A375 melanoma cell transplant experiments and TN-C is able to repress Wnt signaling by DKK1 in tumor and endothelial cells creating a proangiogenic TME." (PMID 35785162, 2022). "DKK1 was significantly expressed in various cancers, and it might also be a biomarker for tumor immunity or even targeted therapy." (PMID 34899842, 2021). "OLR1, STC2, and DKK1 correlate with tumor evolution and immunosuppressive effects." (PMID 34993138, 2021). "DKK1 strongly enhanced the vascularization of Matrigel plugs and tumor growth." (PMID 34093545, 2021). "In these in vitro models, DKK1 could contribute to tumor progression by promoting migration, invasion, proliferation, preventing apoptosis and enhancing cancer stem cell-like properties." (PMID 34093545, 2021). "DKK1 expression led to increased tumor formation and deterioration." (PMID 34093545, 2021). "However, the expression of DKK1 and soluble frizzled‐related proteins decreased in one kind of tumor." (PMID 33639034, 2021). "Besides involving in modulation of T helper cell development, DKK1 was also proven to be a key player in tumor microenvironment through MDSCs manipulation." (PMID 34093545, 2021). "In vivo experiments have also confirmed that NK4 inhibits tumor formation in nude mice, and it may be related to the regulation of DKK1/Wnt1/β-Catenin related pathways." (PMID 34970492, 2021). "A dynamic range of DKK1 signal (H-scores of 0–180) was observed in the tumor cells." (PMID 33972574, 2021). "Moreover, DNA methylation downregulated the expression of Wnt inhibitors including Wnt inhibitory factor 1 (WIF-1), several frizzled-related proteins (SFRP1-5), and Dickkopf-related protein 1 (DKK1) in the tumor cells." (PMID 34051847, 2021). "This experiment confirms that NK4 gene the anti-tumor effect may be related to the regulation of DKK1/Wnt/β-Catenin related pathways, but further experiments are needed to prove this conclusion." (PMID 34970492, 2021). "Furthermore, DKK-1 expression in tumor cells activated Wnt/β-catenin signaling and demonstrated an interaction with AR signaling." (PMID 34357036, 2021). "Possibly, the DKK1 antibody could act on MDSCs to exploit the supportive tumor microenvironment by preventing MDSC accumulation and compromising their inhibitory effect on immune cells." (PMID 34093545, 2021). "A recent study reveals that overexpression of DKK1 could modulate anti-tumor immune populations within the tumor microenvironment by decreasing CD45+ leukocyte infiltration and reducing NK and CD8+ T cells." (PMID 34093545, 2021). "In addition, DKK1 had tumor-promoting activity in in vivo animal models through its effects on tumor growth, metastasis, and angiogenesis." (PMID 34093545, 2021). "This inconsistent result can be attributed to the variance in studies’ characteristics such as sample size, cancer staging, and location of tumor lesions, while it also suggests that the mechanism of DKK1 affecting cancer cells can be varied depending on cancers." (PMID 34093545, 2021). "This could provide a strong basis for developing advance DKK1 inhibitors with high anti-tumor efficacy." (PMID 34093545, 2021). "Additional studies indicated DKK1 could suppress tumor growth and proliferation by inducing apoptosis of cancer cells." (PMID 34093545, 2021). "The oncogenic activity of DKK1 can be blocked by therapeutic intervention in animal tumor models." (PMID 33972574, 2021). "This evidence suggested DKK1 would participate in anti-tumor immunomodulation." (PMID 34093545, 2021).